HOTAIR (HOX transcript antisense RNA)
Diseases named in the same sentence as HOTAIR in open-access papers (continued):
Sharing a sentence is not in itself a finding about the gene and the disease.
esophageal squamous cell carcinoma (46 papers, 2013 to 2025). Esophageal squamous cell carcinoma (ESCC) is a type of esophageal carcinoma (EC) that can affect any part of the esophagus, but is usually located in the upper or middle third. "We also demonstrated a significant association between HOTAIR and the tumor stage as has also been reported in colorectal and esophageal squamous cell carcinoma." (PMID 33670447, 2021). "HOTAIR rs920778 was associated with esophageal cancer and esophageal squamous cell carcinoma risk (Tian, Liu, Liu, Zuo, & Chen, 2019)." (PMID 32394637, 2020). "HOTAIR upregulation is associated with poor patient prognosis in mammary and esophageal squamous cell carcinoma and other malignancies." (PMID 31412811, 2019). "The SNP, rs920778, located within the intron 2 region of HOTAIR, was reported to have a significant association with an increased risk of esophageal squamous cell carcinoma (ESCC) in a Chinese population." (PMID 31013831, 2019). "Moreover, SNP rs920778, which locates in intron 2 of lncRNA HOTAIR, has recently been shown to be associated with esophageal squamous cell carcinoma risk and regulation of HOTAIR expression." (PMID 26430965, 2015). "More importantly, the rs920778TT allele is correlated with higher expression of HOTAIR in the esophageal tissue than the rs920778CC allele, and the HOTAIR rs920778TT carriers are at a higher risk of esophageal squamous cell carcinoma than the HOTAIR rs920778CC carriers." (PMID 25491133, 2014). "In addition, it was found that serum HOTAIR could be used as a diagnostic biomarker in gastrointestinal and esophageal squamous cell carcinoma." (PMID 33670447, 2021). "In esophageal squamous cell carcinoma, Wang and Colleagues reported that HOTAIR promotes the expression of ZEB1 by acting as a ceRNA and negatively regulating miR-130a-5p." (PMID 37308974, 2023). "miRNA-34a is downregulated by HOTAIR in colon cancer and HOTAIR itself is upregulated in esophageal squamous cell carcinoma." (PMID 36980864, 2023). "Several studies report that HOTAIR is upregulated in esophageal squamous-cell carcinoma (ESCC), and that elevated HOTAIR expression is related to advanced TNM stage and poor histological differentiation." (PMID 32117729, 2020). "HOTAIR acts in esophageal squamous cell carcinoma by activating the Wnt/β-catenin signaling pathway." (PMID 28931862, 2017). "A recent study showed that HOTAIR is overexpressed in 96.15% (75/78) of esophageal squamous cell carcinoma patients." (PMID 28938586, 2017). "The aim of this study was to examine HOTAIR expression in patients with esophageal squamous cell cancer (ESCC) and explore its clinical significance." (PMID 23717443, 2013). "In esophageal squamous cell cancer, HOTAIR knockdown may reduce the ability of cells to proliferate, migrate, and invade the extracellular matrix." (PMID 36816362, 2023). "Moreover, the expression level of HOTAIR correlated with esophageal squamous cell carcinoma progression and prognosis." (PMID 25243407, 2014). "CCL18 upregulates the expression of HOTAIR, and the knockdown of HOTAIR alleviates the CCL18-induced invasiveness of Esophageal squamous cell carcinoma (ESCC) cells." (PMID 36997931, 2023). "Likewise, HOTAIR maintains Wnt/β-catenin activated in esophageal squamous cell carcinoma." (PMID 34778043, 2021). "In esophageal squamous cell carcinoma (ESCC), HOTAIR acts as a miR-148a sponge to positively regulate Snail2 expression, enhancing cell invasion and metastasis, and thereby promoting EMT." (PMID 33540611, 2021). "In 78 cases of esophageal squamous cell carcinoma (ESCC) patients, almost all with high expression of HOTAIR in tumor tissues (75/78, 96.15 %), expression level correlated with tumor metastasis, TNM staging, and lower overall survival (OS) rate." (PMID 27686732, 2016).
esophageal squamous cell carcinoma (continued). "Of interest, HOTAIR is capable of reprogramming chromatin organization and promoting cancer cell metastasis which involved in both esophageal squamous cell carcinoma (ESCC) progression and prognosis." (PMID 26172293, 2015). "Through this process, lncRNA HOTAIR could facilitate the glycolysis and tumorigenesis of esophageal squamous cell carcinoma (ESCC) cells in vitro and in vivo." (PMID 38184562, 2024). "HOTAIR can also regulate HK2 expression in esophageal squamous cell carcinoma by combining endogenous miR-125 and miR-143, and then regulate glycolysis of esophageal squamous cell carcinoma to affect the occurrence and development of tumors." (PMID 35093153, 2022). "Additionally, the polycomb repressive complex 2 (PRC2) and lncRNA HOTAIR regulate WIF-1 expression by increasing H3K27 methylation in the promoter region, activating the Wnt/β-catenin signaling pathway in esophageal squamous cell carcinoma (ESCC)." (PMID 37384249, 2023). "HOTAIR can “sponge” miR-130a-5p to regulate ZEB1 and thus promoting malignant progression of esophageal squamous cell carcinoma, while HOTAIR is regulated by chemokine (C-C motif) ligand 18 (CCL18), which plays an important role in tumor progression and metastasis." (PMID 35093153, 2022). "Additionally, HOTAIR has been shown to promote EMT through the activation of Wnt/Notch signaling and its upregulation constitutes a prognostic factor in esophageal squamous cell carcinoma." (PMID 33187205, 2020). "Mechanistically, HOTAIR acted as a ceRNA for miR-130a-5p to derepress ZEB1, promoting EMT in esophageal squamous cell carcinoma (ESCC)." (PMID 35222443, 2022).
liver cancer (41 papers, 2013 to 2025). An epithelial or non-epithelial malignant neoplasm that arises from the liver. "HOTAIR activated the expression of proteins involved in nuclear factor kappa B (NF-κB) and associated with increased tumor cell growth rates in liver cancer." (PMID 36421813, 2022). "Up-regulation of HOTAIR is associated with metastatic progression and low survival rates in breast, colon, and liver cancer patients." (PMID 30180792, 2018). "In the 18 cases of human primary liver cancer, HOTAIR upexpression(100%) was negatively associated with the SETD2 down expression(100%) (Correlation coefficient, R = −1)." (PMID 26172293, 2015). "For instance, lncRNA HOTAIR overexpression is associated with the development of liver cancer." (PMID 31341758, 2019). "In liver cancer, increased expression of HOTAIR has been demonstrated to suppress the expression of miR‐17‐5p, resulting in increased liver cancer cell proliferation and metastasis." (PMID 39347925, 2024). "Through wound scratch and Transwell experiments, we found that the decrease of HOTAIR in liver cancer cells reduced cell migration and invasion ability." (PMID 37576402, 2023). "To gain insight into the biological role of HOTAIR in human liver cancer development, we analyzed the expression of HOTAIR in 30 pairs of liver cancer tissues and adjacent normal hepatic tissues by qRT-PCR." (PMID 37576402, 2023). "As illustrated by RT-qPCR, HOTAIR expression was higher in liver cancer tissues than that in adjacent normal tissues." (PMID 37880710, 2023). "Multiple studies have indicated that overexpression of HOTAIR in liver cancer is positively correlated to poor prognosis, recurrence and tumor progression." (PMID 37880710, 2023). "HOTAIR promotes liver cancer cell proliferation by sponging miR-217-5p, which is reversed by HOTAIR knockdown." (PMID 37190145, 2023). "Consistent with the published data, we confirmed that changes in HOTAIR expression have an impact on the invasion and metastasis of liver cancer cells." (PMID 37576402, 2023). "We also found that NUAK1 was highly expressed by qPCR in 30 pairs of liver cancer tissues compared with adjacent normal tissues and that expressions of HOTAIR and NUAK1 were positively correlated." (PMID 37576402, 2023). "According to bioinformatics analysis, we uncovered that HOTAIR was expressed at high levels in liver cancer tissues, and its expression has also been reported to be closely associated with the development and poor prognosis of liver cancer." (PMID 37880710, 2023). "We found that HOTAIR were more highly expressed in liver cancer tissues compared with adjacent normal tissues." (PMID 37576402, 2023). "Similar to HOTAIR, LSD1 was found to be overexpressed in clinical samples of patients with liver cancer, positively linked to the malignancy degree." (PMID 37880710, 2023). "Taken together, our experimental results showed that HOTAIR impeded the radiosensitivity of liver cancer cells by maintaining its stemness." (PMID 37880710, 2023). "After HOTAIR knockout, the expression of miR-217 increased, and the sensitivity of sorafenib in the treatment of liver cancer increased." (PMID 35093153, 2022). "Short-term recurrence after liver resection or liver transplantation in patients with HCC is related to the increasing expression of HOTAIR and the decreased expression of HOTAIR leads to the apoptosis of liver cancer cell lines." (PMID 34799469, 2021). "It has been reported that lncRNAs including HULC, HOTAIR and LncTCF7 are highly expressed in liver cancer samples 27, 31-33." (PMID 31695772, 2019). "In another study, RNA-protein complexes formed with HOTAIR were regulated by the RNA helicase DEAD box protein 5 (DDX5), and associated with HBV biosynthesis and poor prognosis in HBV-mediated liver cancer." (PMID 30159431, 2017).
liver cancer (continued). "Of the large number of lncRNAs identified so far, some (e.g., TUG1 and HOTAIR) have been shown to play very important roles in multiple aspects of liver cancer such as tumourigenesis, tumour recurrence and drug resistance." (PMID 29061150, 2017). "Functional knockdown of HOTAIR expression in liver cancer cells corresponded with decreased cell viability and invasion, increased TNF-α induced apoptosis, and heightened sensitivity to chemotherapeutic agents." (PMID 30159431, 2017). "In summary, our present data indicated that IKKα plus IKKβ, and IKKγ promotes/inhibits liver cancer stem cells malignant progression through altering telomere length and telomerase activity dependent on HOTAIR, with clinic implications." (PMID 27367027, 2016). "Taken together, HOTAIR is required for IKKα plus IKKβ and IKKγ to control telomerase activity and telomere length in liver cancer stem cells." (PMID 27367027, 2016). "Taken together, these observations suggest that HOTAIR operates the oncogenic action of IKKα, IKKβ, and IKKγ in liver cancer stem cells." (PMID 27367027, 2016). "Our results indicate HOTAIR causes microsatellite instability (MSI) and abnormral expression of cell cycle related gene, e.g. CDK2, CyclinE, CDK4, CyclinD1, PCNA, ppRB, E2F1 in liver cancer stem cells." (PMID 26172293, 2015). "HOTAIR has been shown to increase the invasion of many types of cancer cells including pancreatic, breast, colon, and liver cancer cells." (PMID 25405331, 2015). "Taken together, these observations suggest that the overexpressed HOTAIR oncogenic action was abrogated by the overexpression of SETD2 in human liver cancer stem cells." (PMID 26172293, 2015). "This understanding the novel functions of HOTAIR will help in the development of new liver cancer therapeutic approaches." (PMID 26172293, 2015). "This study provides evidence for HOTAIR to promote tumorigenesis via downregulating SETD2 in liver cancer stem cells." (PMID 26172293, 2015). "In this study, we identify that HOTAIR promotes human liver cancer stem cell malignant growth through downregulation of SETD2, the enzyme that trimethylates histone H3 lysine 36 (H3K36me3), is required for ATM activation upon DNA double-strand breaks (DSBs)." (PMID 26172293, 2015). "The suppression of HOTAIR in liver cancer cells reduces cell viability and invasion, sensitizes the cells to TNF-induced apoptosis and increases chemotherapeutic sensitivity." (PMID 23717443, 2013). "The lncRNAs of interest for this test—namely ANRIL, H19, HOTAIR, HULC, MALAT1, WISPER, and ZFAS1—were initially identified in other pathologies, as evident in some of their names, highly upregulated in liver cancer (HULC), or metastasis associated lung adenocarcinoma transcript 1 (MALAT1)." (PMID 40271126, 2025). "Our results showed that the lncRNA HOTAIR is overexpressed in liver cancer tissues and cell lines." (PMID 37576402, 2023). "Expression of HOTAIR was determined in liver cancer tissues and CSCs." (PMID 37880710, 2023). "Therefore, in the nucleus, HOTAIR tethers protein complexes to chromatin to repress or activate gene transcription, thus controlling the progression of liver cancer." (PMID 37880710, 2023). "In liver cancer tissues and cells, HOTAIR is overexpressed, and miR-217-5p is downregulated." (PMID 37190145, 2023). "The role of in vivo liver cancer progression was also validated by HOTAIR knockdown." (PMID 37190145, 2023). "However, in liver cancer cells with HOTAIR knockout, it was found that the expression of E-cadherin increased while the expression of Vimentin decreased, and the drug resistance of sorafenib decreased." (PMID 35093153, 2022).
liver cancer (continued). "Studies have found that HOTAIR can “sponge” miR-206/miR-613 in liver cancer cells, thus destroying the binding site of miR-206/miR-613 and OATP1B1 mRNA 3’-UTR, affecting the binding of miR-206/miR-613 and OATP1B1 mRNA 3′-UTR, and then eliminating the stimulation of LncRNA HOTAIR on OATP1B1 protein." (PMID 35093153, 2022). "Moreover, the depletion of HOTAIR in HCC cell lines reduced cell susceptibility to TNF-α-induced apoptosis, while it increased the chemotherapeutic sensitivity of liver cancer cells to cisplatin and doxorubicin." (PMID 34367966, 2021). "Recent studies have also found that the expression level of HOTAIR is not only related to postoperative prognosis evaluation of liver cancer patients, but also related to its resistance to platinum preparations and doxorubicin and invasion and metastasis of liver cancer cells." (PMID 32700738, 2020). "To investigate whether IKKα, IKKβ, and IKKγ influence on HOTAIR expression, we first performed IP assay in liver cancer stem cells." (PMID 27367027, 2016). "The present study depicts a novel provides evidence for HOTAIR to play tumorigenesis roles by downregulating SETD2 in liver cancer stem cells, which may have potential therapeutic significance." (PMID 26172293, 2015). "Although reduction of SETD2 may partly contribute to HOTAIR-medicated promotion of liver cancer stem cell growth, our findings in this study provide novel evidence for an active role of SETD2 in HOTAIR-mediated promotion of liver cancer stem cell growth." (PMID 26172293, 2015). "It provides evidence for HOTAIR to play tumorigenesis roles via downregulating SETD2 in liver cancer stem cell, which may have potential therapeutic significance." (PMID 26172293, 2015). "Additionally, inhibition of HOTAIR expression in liver cancer cell lines increases the chemosensitivity of tumor cells to cisplatin and doxorubicin." (PMID 25422887, 2014). "In summary, the lncRNA HOTAIR is important in breast, gastroenteric, and liver cancers." (PMID 25334066, 2014). "Here we demonstrated that HOTAIR and NUAK1 were positively correlated in liver cancer tissues and cell lines and that the addition of NUAK1 inhibitor reversed the effect of high HOTAIR expression on EMT-related proteins." (PMID 37576402, 2023). "In this study, through transcriptome sequencing data and in vitro experiments, we found that HOTAIR were more highly expressed and there is significantly positive relationship between HOTAIR and NUAK1 in liver cancer tissues and cell lines." (PMID 37576402, 2023). "LSD1 has been reported to interact with HOTAIR in cancer cells, and the expression of LSD1 is enhanced in liver cancer cells." (PMID 37880710, 2023). "We also showed that HOTAIR recruiting and binding PRC2 (EZH2) epigenetically represses miR-145-5p, which controls the target NUAK1, thus contributing to liver cancer cell-EMT process and accelerating tumor metastasis." (PMID 37576402, 2023). "Additional experiments revealed that HOTAIR knockdown, miR-145-5p upregulation and NUAK1 inhibition all repressed migration, invasion and metastasis and reversed liver cancer cell-EMT in SNU-387 and HepG2." (PMID 37576402, 2023). "We demonstrated a positive regulatory relationship between HOTAIR and NUAK1 in liver cancer tissues and cells and showed that HOTAIR regulates the miR-145-5p /NUAK1 axis through PRC2 (EZH2)." (PMID 37576402, 2023). "Further, the expression of HOTAIR was regulated by JMJD6–BRD4 complex, and the JMJD6 inhibitor contributed to the radiosensitivity of liver cancer cells by suppressing the expression of HOTAIR and ERK2 (MAPK1)." (PMID 37880710, 2023). "In this sudy, through transcriptome sequencing data and in vitro experiments, we found that HOTAIR were more highly expressed and there is significantly positive relationship between HOTAIR and NUAK1 in liver cancer tissues and cell lines." (PMID 37576402, 2023).